CXCR4 (C-X-C motif chemokine receptor 4)
Diseases named in the same sentence as CXCR4 in open-access papers (continued):
Sharing a sentence is not in itself a finding about the gene and the disease.
lymph node metastasis (continued). "Cytoplasmic CXCR4 expression was significantly correlated with nitrotyrosine levels and lymph node metastasis." (PMID 19025611, 2008). "Formation of the biomarker nitrotyrosine was also correlated with CXCR4 expression and lymph node metastasis in vivo." (PMID 19025611, 2008). "Lymph node metastasis was correlated with cytoplasmic CXCR4 expression (p = 0.0144), VEGF-C expression (p = 0.0123), and recombination of cytoplasmic CXCR4 and VEGF-C expression (p = 0.0081)." (PMID 19025611, 2008). "In our study, cytoplasmic CXCR4 expression was thought to be critical for lymph node metastasis and the patients' poor prognosis in comparison with nuclear CXCR4 expression." (PMID 19025611, 2008). "Multivariate Cox regression analysis of all covariates focusing on DFS identified the following as independent significant prognostic factors: tumor size, p = 0.0347: lymph node metastasis, p = 0.0007: and cytoplasmic CXCR4 expression, p = 0.0465." (PMID 19025611, 2008). "Recently a positive correlation between lymph node metastasis and a recombination of CXCR4, VEGF, and MMP-9 was reported." (PMID 19025611, 2008). "Recombination of cytoplasmic CXCR4 and VEGF-C expression was correlated with lymph node metastasis more strongly than cytoplasmic CXCR4 only or VEGF-C only." (PMID 19025611, 2008). "In particular, they advocated a role for chemokine receptor 7 (CCR7) in lymph node metastasis, CXCR4 in pulmonary metastasis, and CCR10 in skin metastasis." (PMID 15978137, 2005). "The chemokine receptor CXCR4 has been shown to be involved in tumor growth and metastasis via tumor angiogenesis, and its expression on oral squamous cell carcinoma (OSCC) cells was associated with recurrence and lymph node metastasis." (PMID 39001388, 2024). "CXCR4 expression correlated with lymph node metastases (p = 0.0237) and stage (p = 0.0054)." (PMID 35877436, 2022). "Of the 48 cancer tissues, 31 (64.58%) were CXCR4 positive, and, in addition, CXCR4 expression correlated with more aggressive histology; that is, it was significantly higher in patients with squamous cell carcinomas and lymph node metastasis." (PMID 36140541, 2022). "In a related study, CCR7 expression was observed to be highly variable in 96 colorectal carcinoma patients and although CXCR4 expression was associated with lymph node metastasis, in this study, there was no such correlation for CCR7." (PMID 35203305, 2022). "In China, high nuclear CXCR4 was associated with negative lymph node metastases, while high cytoplasmic CXCR4 expression was associated with patients with lymph node metastases." (PMID 33773539, 2021). "In addition, high levels of CXCR4 have been closely related to lymph node metastasis, a high T stage, and patient prognosis." (PMID 32368286, 2020). "In addition, there was a positive correlation between high CXCR4 expression and lymph node metastasis (p=0.033)." (PMID 31949484, 2020). "In addition, high CXCR4 expression was positively correlated with lymph node metastasis and advanced TNM stages (II-III)." (PMID 31949484, 2020). "Losartan may provide a safer and more economic strategy for CXCR4-induced lymph node metastasis and relapse." (PMID 31219799, 2019). "Therefore, our data strongly suggest that blocking AGTR1 reduces lymph node metastasis invivo and that this effect is likely mediated via CXCR4/SDF-1α." (PMID 31219799, 2019). "Thus, CXCR4 expression positively correlated with lymph node metastasis (OR: 2.55; 95% CI: 1.56–4.15; P = 0.0002; I2 = 26%) and advanced UICC stage III and IV (OR: 3.40; 95% CI: 1.67–6.92; P = 0.0007; I2 = 0%)." (PMID 26091099, 2015). "The expression level of CXCR4 is significantly correlated with lymph node metastasis." (PMID 24591761, 2014). "It would be interesting to check whether expression of CXCR4 and uPAR are related to any specific metastatic pattern other than the lymph node metastasis seen in our study." (PMID 24709997, 2014).
lymph node metastasis (continued). "CXCR4 expression was significantly associated with lymph node metastasis and TNM stage (0.01 < p < 0.05), but not with age, menopausal status, first term birth age, tumor size, and tumor stage (p > 0.05)." (PMID 24810923, 2014). "Moreover, the expression of several chemokine receptors has been associated with a greater risk of developing regional and distant metastases as lymph node metastasis (CCR7; CCR10,; CXCR3 and CXCR4;), pulmonary metastasis (CXCR4) or skin metastasis (CCR10;)." (PMID 24559071, 2014). "Additionally, a significant correlation between the expression pattern of the CXCL12/CXCR4 axis with lymph node metastasis was identified (P<0.05), excluding gender, age, tumor node metastasis (TNM) stage and differentiation (all P>0.05)." (PMID 23181100, 2012). "Repeated in many papers is the fact that cytoplasmic CXCR4 staining is noted to associate with lymph node metastasis while nuclear CXCR4 staining has not had significant results." (PMID 22295222, 2011). "Moreover, our data also indicate that the combined high expression of HIF-1α, CXCR4, and VEGF is significantly associated with lymph node metastasis and distant metastasis." (PMID 20953377, 2010). "Therefore we examined CXCL12 and CXCR4 immunoreactivity in a subset of 61 matching lymph node metastases." (PMID 20386750, 2010). "Previously, we reported that lymph node metastasis is correlated with cytoplasmic CXCR4 expression." (PMID 19580679, 2009). "The extent of CXCR4 overexpression correlated with bone metastases (correlation coefficient: 0.551; P < 0.001), margin status (correlation coefficient: 0.206;P = 0.005), and hilar lymph node metastases (correlation coefficient: 0.198; P = 0.008)." (PMID 19508713, 2009). "Similarly, lymph node metastasis and cytoplasmic CXCR4 expression were identified as independent prognostic factors for OS (lymph node metastasis; p = 0.0107, cytoplasmic CXCR4 expression; p = 0.0263)." (PMID 19025611, 2008). "Patients with residual lymph node metastases after chemotherapy, CCR5, or CXCR4 expressions on tumors have shown a worse outcome compared to others." (PMID 39001456, 2024). "In total, there were eighteen L‐R pairs decreased in NPC patients with lymph node metastasis, and the communication probability of five pairs including MIF‐(CD74 + CXCR4), MIF‐(CD74 + CD44), LGALS9‐CD45, IL16‐CD4 and CCL19‐CCR7 were increased in NPC_LNM." (PMID 39392128, 2024). "The expression of CXCR-4, PKC-δ and CD133 were found to be higher in poorly differentiated and lymph node metastasis-positive cases." (PMID 34885003, 2021). "In univariate analysis, patients with high CXCR4 expression, solid ASC subtype, and lymph node metastasis exhibited significantly worse DFS and OS compared with their counterparts." (PMID 31949484, 2020). "CXCR4 expression significantly correlated with PNI as well as other major invasive parameters, including lymph node metastasis, TNM stage and vascular invasion in PCa patients." (PMID 25605248, 2015). "In the univariate survival analysis, lymph node metastasis, advanced TNM stage, positive resection margins, poor tumor differentiation, CXCR4 expression and EGFR/CXCR4 coexpression were significant prognostic factors for poor DFS and OS." (PMID 25679210, 2015). "Immunohistochemical analysis showed the co-expression of CXCR4 and CXCL12 correlated with lymph node metastasis and TNM stage (p < 0.01)." (PMID 24810923, 2014). "Nrp2 expression was correlated with lymph node metastasis, VEGF-C expression, and cytoplasmic CXCR4 expression." (PMID 19580679, 2009). "Nrp2 expression was correlated with lymph node metastasis (p = 0.0389), VEGF-C expression (p < 0.001), and cytoplasmic CXCR4 expression (p < 0.001)." (PMID 19580679, 2009). "Nrp2 expression was significantly correlated with lymph node metastasis, VEGF-C expression, and cytoplasmic CXCR4 expression." (PMID 19580679, 2009).
lymph node metastasis (continued). "Lymph node metastasis, VEGF-C expression, cytoplasmic CXCR4 expression, and also Nrp2 expression as shown in this study (p = 0.0268) had significant prognostic value for OS." (PMID 19580679, 2009). "Survival analysis was performed on 113 patients and the following variables were examined: Nrp2 expression, tumor size, lymph node metastasis, hormonal status, histological grade, VEGF-C expression, and cytoplasmic or nuclear CXCR4." (PMID 19580679, 2009). "The expression level of CXCR4 was not significantly correlated with gender, lymph node metastasis, liver metastasis and clinical stage." (PMID 38524630, 2024). "The CXCR-4 expression was found to be higher in cases with lymph node metastasis compared with cases without lymph node metastasis." (PMID 34885003, 2021). "Since then, CCR7 has been suggested as a biomarker for lymph node metastasis, but, unlike CXCR4, few potential therapies have been developed." (PMID 34298676, 2021). "The CXCR4 expression level was significantly higher in non-small cell lung cancer (NSCLC) tissues from the patients with lymph node metastasis than in those without metastasis." (PMID 32943996, 2020). "LUAD patients with lymph node metastasis had higher plasma levels of exo-hsa_circRNA_0056616 and CXCR4 expression than those without." (PMID 32943996, 2020). "In our study, only five patients were observed with lymph node metastasis and six with distant metastasis, which is not enough to evaluate the relationship between CXCR4 nuclear localization and clinical data." (PMID 23039915, 2012). "Statistical analysis has shown that there was a significant difference between the mean CXCR4 mRNA levels for all groups (lymph node metastasis group or distant metastasis group vs negative control group, resp., P < .05)." (PMID 20953377, 2010). "An enhanced-aggressiveness for lymph node metastasis by recombination of VEGF-C and CXCR4 may be also speculated." (PMID 19025611, 2008). "Furthermore, lymph node metastasis was correlated with cytoplasmic CXCR4 expression, VEGF-C expression, and recombination of cytoplasmic CXCR4 and VEGF-C expression in this study." (PMID 19025611, 2008). "We and others found the expression pattern of CXCR4 to be significantly correlated with the degree of lymph node metastases but not with haematogenous metastases." (PMID 15987445, 2005). "Additionally, CXCR4 expression was observed in tumor samples from patients; 68.90% of patients had lymph node metastasis, while 31.10% did not." (PMID 35681259, 2022). "However, CXCR4-silenced cells exhibited decreased basal and SDF-1 directed cell migration in transwell assay, which was parallel to our finding that CXCR4 was positively correlated with lymph node metastasis in clinic." (PMID 31949484, 2020). "However, the correlation between the expression of CXCR4 mRNA and lymph node metastasis or UICC stage was not statistically significant (P>0.05)." (PMID 23761820, 2013). "However, the correlation between the expression of the CXCR4 protein and lymph node metastasis or UICC was not statistically significant (P>0.05)." (PMID 23761820, 2013). "Notably, numerous studies have reported the expression of CXCR4 in tumor cells in oral squamous cell carcinoma (OSCC), a prevalent form of oral cancer, especially in cases with CXCR4/stromal cell-derived factor 1 expression, linking it to recurrence and lymph node metastasis." (PMID 39001388, 2024). "However, there were more high CXCR4 expression samples among patients with vascular invasion or lymph node metastasis (63.6 and 66.7%, respectively) than in the non-vascular invasion or lymph node metastasis groups (32.1 and 21.3%; P = 0.001 and P < 0.001 for the two groups, respectively)." (PMID 25471741, 2014). "Simultaneously, CXCR4 expression showed a significant increase in OSCC patients with lymph node metastasis and a T3 tumor stage compared to those without lymph node metastasis and patients with T1–T2 stages." (PMID 38673838, 2024).
lymph node metastasis (continued). "We found that higher levels of CXCR4, RhoA, RhoGEF, PI3K, and ROCK correlated positively with TNM stage (p < 0.05) and lymph node metastasis (p < 0.05) but not with age, gender, tumor size or tumor differentiation." (PMID 27517626, 2016).
Stroke (75 papers, 2010 to 2026). Sudden impairment of blood flow to a part of the brain due to occlusion or rupture of an artery to the brain. "It interacts with CXCR4, and the two are associated with various cancers, as well as other disease states such as coronary artery disease, stroke, inflammation and human immunodeficiency virus (HIV)." (PMID 32098047, 2020). "This was illustrated in a recent study, where C-X-C chemokine receptor type 4 (Cxcr4)-deficient stroke mice showed decreasing monocyte infiltration and increasing expression of microglia pro-inflammatory factors that translated into worse functional outcomes." (PMID 32357544, 2020). "CXCR4 is important for the attraction of the NK cells, and other innate immune cells towards stroke, indirectly affecting microglial function and was shown in both studies to be positively associated with stroke recovery." (PMID 36631780, 2023). "Using Cdh5CreERT2;Cxcl12flox mice, in which Cxcl12 was specifically deleted in BBB endothelial cells, plus a mouse model with Cxcr4-deficient NKp46+ cells, we demonstrated that BBB CXCL12–CXCR4 axis was essential for the influx of NK cells into the stroke lesion." (PMID 36631780, 2023). "However, loss of CD13 led to reductions in post-stroke angiogenesis by reducing CXCL12/CXCR4 signaling." (PMID 37817190, 2023). "CXCR4 not only modulates the neuromodulation, neuroprotection, and neuronal-glial interaction in normal conditions, it is also involved in the neurological disorder caused by human immunodeficiency virus infection, tumor, stroke, and multiple sclerosis." (PMID 29386025, 2018). "Furthermore, SDF-1α/CXCR4 signaling activates endothelial nitric oxide synthase which is a key enzyme maintaining homeostasis by inducing vasodilatation and whose impairment is implicated in the pathogenesis of stroke." (PMID 29776406, 2018). "Mechanistically, microglia recruited B cells into ischemic lesions through MIF-CD74/CXCR4 signaling during the early phase of stroke, while IFN-related pathways in B cells further drove neuroinflammation and brain injury." (PMID 41766668, 2026). "MSX-122 is a partial CXCR4 antagonist which has been tested in pre-clinical stroke models and demonstrated reduced neutrophil infiltration." (PMID 41256885, 2025). "CXCR4 overexpression on SCs through the SDF-1 α-CXCR4 axis can enhance cell homing efficiency following a stroke." (PMID 39852564, 2025). "Similar to GF mice, neutrophils in microbiota-depleted stroke mice expressed lower levels of Ly6G and CXCR4, indicating a juvenile phenotype." (PMID 40410847, 2025). "Our findings suggest that the TGF‐β‐mediated profibrotic activity of macrophages and CXCR4‐driven NET formation in neutrophils are associated with distinct patterns of immunothrombosis in LAA and CE strokes, respectively." (PMID 41329022, 2025). "Collectively, our findings of subtype‐specific elevation of CXCR4 highlight the role of neutrophils in promoting thrombus formation and maintaining stability in CE stroke." (PMID 41329022, 2025). "Simultaneously, the role of the SNHG17/miR-452-3p/CXCR4 axis in IS warrants further exploration and study, with the hope of uncovering additional therapeutic targets to bring more treatment options to stroke patients." (PMID 39897488, 2025). "Neutrophils in microbiota-colonized GF mice expressed higher levels of maturation markers Ly6G, LFA-1, and CXCR4 compared to GF stroke mice." (PMID 40410847, 2025). "After a stroke, CXCR4 overexpression on SCs will improve cell homing efficiency via the SDF-1α-CXCR4 axis." (PMID 38357525, 2024). "Overall, leveraging the multifaceted neurovascular protective effects of endogenous SDF‐1α/CXCR4 signaling presents a promising avenue for developing stroke therapies to maintain BBB integrity after ischemia." (PMID 38379112, 2024).
Stroke (continued). "Our data show a role for blood–brain barrier-derived CXCL12 in attracting protective NK cells to ischemic brain lesions and identifies a new CXCL12/CXCR4-mediated component of the innate immune response to stroke." (PMID 36631780, 2023). "Treatment with exosomes secreted by IPSC-derived MSCs demonstrated a reduction in infarct volume, an improved spontaneous walking ability, and enhanced angiogenesis through the expression of VEGF and CXCR4 proteins in a mouse model of stroke." (PMID 38136654, 2023). "CXCR4-overexpressing, cell-membrane-coated nanoparticles are another biomimetic drug delivery system commonly used in stroke treatment." (PMID 36839943, 2023). "CD13-deficient mice had an increased percentage of CXCL12+cells but a reduced percentage of CXCR4+cells and decreased angiogenesis at day 30 post-stroke." (PMID 37817190, 2023). "CXCR4 promoted initial monocyte infiltration and subsequent territorial restriction of monocyte-derived macrophages to infarct tissue in the stroke brain." (PMID 37305740, 2023). "Then, we treated mice with the CXCR4 antagonist Plerixafor or saline twice daily from the day of stroke until euthanasia two weeks later." (PMID 37816732, 2023). "In the ipsilateral hemisphere, the percentage of CXCR4+ ECs was lower in the CD13KO mice compared to the wild-type after stroke." (PMID 37817190, 2023). "To investigate the role of endothelial cell (EC) CXCL12/CXCR4 pathway after stroke, we then gated on brain ECs as described." (PMID 37817190, 2023). "The expression of the chemokine CXCL12 and its receptor CXCR4 within the brain increases after stroke, which plays a critical role in the migration of monocytes to brain parenchyma." (PMID 36631780, 2023). "CXCL12, which was one of three genes in the pathway, and its receptor CXCR4, which is also the coreceptor of HIV, participate in the pathogenesis of CNS disorders such as HIV-associated encephalopathy, brain tumor, stroke, and multiple sclerosis." (PMID 35456082, 2022). "Hypoxic preconditioning of MSCs resulted in the up-regulation of HIF-1α, VEGF, erythropoietin (EPO), stromal-derived factor-1 (SDF-1), and C-X-C chemokine receptor type 4 (CXCR4), thus potentiating their pro-angiogenic capacities in stroke rodents." (PMID 35986375, 2022). "CXCR4 overexpression in MSCs resulted in increased angiogenesis and neuroprotection in a stroke animal model." (PMID 36499667, 2022). "Following stroke, an accumulation of CXCR4 positive cells, including neurons, is observed in the peri-infarct area accompanied with increased levels of CXCL12, the endogenous ligand of the CXCR4." (PMID 34417725, 2021). "CXCR4 provides neuroprotective effects, which can alleviate brain injury and inflammation induced by stroke." (PMID 34795842, 2021). "We observed increased CXCR4 protein levels in the peri-infarct area of mice subjected to PT, 14 days after stroke, compared to sham-operated mice." (PMID 34417725, 2021). "CXCR4 distinguishes hematopoietic stem cell-derived monocytes from microglia and reveals monocyte immune responses to experimental stroke." (PMID 34539341, 2021). "A CXCR4 antagonist reverses the neurogenesis and behavioral recovery produced by forced limb use following rodent stroke." (PMID 31595394, 2020). "It has been concluded that strokes cause elevation of CXCR4+ VSELS and numbers positively correlated with stroke severity." (PMID 32218149, 2020). "We did demonstrate the involvement of the SDF-1α/CXCR4 pathway in improved stroke outcomes after linagliptin treatment." (PMID 29776406, 2018). "This indicates that improved stroke outcome by linagliptin occurs via the activation of the SDF-1α/CXCR4 pathway." (PMID 29776406, 2018). "Blocking of SDF-1α/CXCR4 pathway abolished the positive effects of linagliptin on upper-limb function and histological outcome after stroke." (PMID 29776406, 2018).